PPARG (peroxisome proliferator activated receptor gamma)
Diseases named in the same sentence as PPARG in open-access papers (continued):
Sharing a sentence is not in itself a finding about the gene and the disease.
intracerebral hemorrhage (15 papers, 2008 to 2024). A cerebrovascular disorder characterized by bleeding into one or both cerebral hemispheres including the basal ganglia and the cerebral cortex. "PPARγ has a pleiotropic role in intracerebral hemorrhage (Zhaoet al., 2015) and ischemic brain injury (Culmanet al., 2007)." (PMID 33224479, 2020). "PPARγ agonists also increased neuron survival anddecreased lesion sizes in models of Parkinson's disease, central inflammation, intracerebral hemorrhage, and cerebral ischemia." (PMID 18401444, 2008). "Previous studies have documented that PPARγ plays a pivotal role in reducing inflammation, and treatment with PPARγ agonists may benefit intracerebral hemorrhage patients by reducing NF‐κB activation and cytokine levels." (PMID 39107960, 2024). "ARA and one of its metabolites, 15(S)-hydroxyeicosatetraenoic acid [15(S)-HETE], activate the nuclear receptor peroxisome proliferator-activated receptor-γ (PPARγ), which has anti-inflammatory benefits and provides neuroprotection in a rat model of intracerebral hemorrhage." (PMID 32117837, 2020). "Previous studies have reported that PPARγ and NRF2 play a key role in reducing lipid peroxidation and ferroptosis in different diseases, including cancer, intracerebral hemorrhage, and diabetic cardiomyopathy." (PMID 38594496, 2024). "In order to determine the therapeutic effect of pioglitazone as an agonist of PPARγ on ICH rats, we used the rat model of intracerebral hemorrhage induced by autologous blood injection into the striatum in vivo." (PMID 35517804, 2022). "Indeed, PPARγ-induced reductions in neutrophil, T-cell, and macrophage infiltration have been shownin animal studies of experimental allergic encephalomyelitis (EAE, an animalmodel of MS) and intracerebral hemorrhage." (PMID 18401444, 2008).
squamous cell carcinoma (14 papers, 2008 to 2024). A carcinoma arising from squamous epithelial cells. "The authors presented their results on the A431 human squamous cell carcinoma cell line, which showed that stable expression and activation of PPARβ/δ or PPARγ led to reduced carcinogenicity." (PMID 39062500, 2024). "This genomic approach supports previous studies indicating that PPARγ is an important tumor suppressor in cutaneous carcinogenesis, leading to actinic disease and squamous cell carcinoma." (PMID 39195246, 2024). "This is the first study, to our knowledge, examining the ability of PPARγ activation to induce differentiation markers and to antagonize the TGF-β1-mediated changes associated with the EMT process in a human squamous carcinoma cell line." (PMID 37048080, 2023). "Later studies confirmed this mechanism of anoikis induction by PPARγ antagonists in squamous-cell carcinoma." (PMID 35954274, 2022). "An immunohistological analysis of 147 primary NSCLC tumor specimens also revealed that PPARγ expression correlates with histological type and grade; well-differentiated adenocarcinoma shows higher PPARγ expression than poorly differentiated adenocarcinoma or squamous cell carcinoma." (PMID 27698657, 2016). "The results of the Western immunoblot test performed on tissue material revealed significant differences in the expression of selected proteins involved in apoptosis-related proline metabolism (PRODH/POX, PPARγ, HIF-1α) between squamous cell carcinoma and normal mucosa." (PMID 31935820, 2020).
alopecia (13 papers, 2012 to 2025). Hair loss usually from the scalp. "Local skin inflammation is indeed observed in PpargΔ/Δ mice and was associated with PPARγ-dependent scarring alopecia." (PMID 30483254, 2018). "In addition, loss of PPARγ in the epidermis has been linked to the regulation of other marker genes associated with the asebia phenotype, increased transepidermal water loss, alopecia, dandruff and inflammatory skin lesions." (PMID 36552866, 2022). "Their findings suggest that the targeted deletion of PPARγ (a transcription factor involved in regulating lipid homeostasis) in follicular stem cells leads to scarring alopecia." (PMID 40953083, 2025). "Here, in PPARγ knockout mice, an aseptic skin phenotype with alopecia was observed, which is consistent with the results from other authors." (PMID 36552866, 2022). "Another study demonstrated that PPARG mRNA is significantly decreased in human lichen planopilaris, a form of scarring (cicatricial) alopecia." (PMID 34445339, 2021). "Furthermore, tissue-specific deletion of PPARγ in bulb stem cells resulted in scarring alopecia and sebaceous gland hypoplasia resembling human lichen planopilaris, a scarring (cicatricial) alopecia in which PPARγ is also downregulated." (PMID 36552866, 2022). "Because the targeted deletion of PPARγ in follicular stem cells in mice causes a scarring alopecia‐like phenotype 23, IBMX‐mediated PPARγ expression may support the gene expression required for hair formation." (PMID 31730301, 2020). "Having found that the essential fact in FFA is the dysfunction of PPARγ andthat the function of this receptor is linked to stimulation of DHEA, it is vital todefine its participation in the development of fibrosis in this alopecia." (PMID 28099600, 2016). "Our previous studies showed that the hair follicles and sebaceous glands of PPARγ knockout mice (a mouse model of scarring alopecia) have decreased expression of lipid metabolic genes and increased expression of inflammatory genes suggesting that these changes are caused by loss of PPARγ signaling." (PMID 22685570, 2012). "Indeed, the deletion of PPARγ in K15-bulge stem cells in mutant mice results in an LPP-like skin phenotype with progressive hair loss, perifollicular inflammation and scarring alopecia." (PMID 22685570, 2012). "On the other hand, there is a hypothesis suggesting that the abnormal decrease in DHEA during postmenopausal stages, which typically stimulates PPARc (peroxisome proliferator-activated receptor gamma), might play a role in the development of Frontal Fibrosing Alopecia." (PMID 38248773, 2024). "Moreover, HF stem cell-specific PPARγ deletion in mice resulted in scarring alopecia." (PMID 31335913, 2019).
atopic dermatitis (13 papers, 2011 to 2026). "Previous reports indicated that a PPARγ agonist inhibited atopic dermatitis in mice through the suppression of mast cell maturation and mediator release." (PMID 31766714, 2019). "Given that both galectin-12 knockdown and PPARγ inhibition (GW9662) lead to reduced CCL26 expression and improved atopic dermatitis symptoms galectin-12 might sustain Th2 immune responses by reinforcing PPARγ activation in sebocytes." (PMID 40563477, 2025). "Although direct evidence for their activity in keratinocytes or atopic dermatitis is limited, their predicted targeting of CASP3 and PPARG suggests a role in fine-tuning apoptosis–lipid metabolism cross-talk, as well as in context-specific regulation of barrier repair pathways." (PMID 41226767, 2025).
brain injury (13 papers, 2012 to 2025). Acute and chronic (see also brain INJURIES, CHRONIC) injuries to the brain, including the cerebral hemispheres, CEREBELLUM, and brain STEM. "For instance, in traumatic brain injury, phillyrin inhibits the phosphorylation of NF‐κB, activates the PPARγ signaling pathway, and suppresses microglia‐induced inflammatory damage." (PMID 41142018, 2025). "In animal models, PPARγ agonists reduced damage, oxidative stress and neurological deficits and promoted neuronal survival and functional recovery after ischemic brain injury." (PMID 36768419, 2023). "Although no studies have been published regarding the relationship between artichoke and Klotho and PPARγ activity, recent studies demonstrated that phenolic compounds have neuroprotective effects in brain injuries by upregulating Klotho and PPARγ expression." (PMID 36556233, 2022). "Consistently, in a model of brain trauma, whose pathogenesis also involves nitrosative stress, PPARγ agonist pioglitazone demonstrated beneficial functions through mechanisms not related to PPARγ activation." (PMID 30410641, 2018). "PPARγ agonists have been documented to have actions that do not require PPARγ activation in previous studies, including in a model of brain trauma where pioglitazone reduced the inflammatory response in a manner unaltered by the administration of the PPARγ antagonist T0070907." (PMID 22417924, 2012).
diabetic retinopathy (13 papers, 2008 to 2025). "1,8-cineole improves diabetic retinopathy by suppressing ferroptosis in retinal pigment epithelial cells via the PPARγ/TXNIP pathway." (PMID 41438090, 2025). "In diabetic retinopathy, PPARγ expression is suppressed under hyperglycemia, whereas activation by rosiglitazone delays disease progression, supporting its potential as a therapeutic target." (PMID 41438090, 2025). "The impact of PPARγ is not limited to cancer, since also other pathologies such as diabetic retinopathy were shown to be influenced in their ferroptotic behavior by PPARγ." (PMID 37554158, 2023). "The association of non-synonymous substitution polymorphism rs1801282 (c.34C>G, p.Pro12Ala) in exon 4 of the peroxisome proliferator activated receptor gamma gene with diabetic retinopathy (DR) has been reported inconsistently." (PMID 23559865, 2013). "Both PPARα and PPARγ have been proposed as candidates for treating diabetic retinopathy." (PMID 41438090, 2025). "Costa and Ciccodicola, on the other hand, investigated whether PPARγ is essential to diabetic retinopathy, finding, however, a beneficial role." (PMID 39062500, 2024). "PPARγ plays an essential role in the pathogenesis of diabetic retinopathy (DR)." (PMID 36088760, 2022). "PPARG+/- knockout mice had greater leukostasis and leakage than wild-type mice, and suppression of PPARG has been shown to be involved in the pathogenesis of diabetic retinopathy and OIR." (PMID 32190036, 2020). "Therapeutic targeting of PPARγ may be beneficial to diabetic retinopathy." (PMID 18309374, 2008). "These resultsprovide strong evidence to support the theory that PPARγactivity plays an important role in the pathogenesis of diabetic retinopathy andintroduce the novel possibility that the therapeutic targeting of PPARγ maybe beneficial to diabetic retinopathy." (PMID 18309374, 2008).
glomerulosclerosis (13 papers, 2007 to 2025). A hardening of the kidney glomerulus caused by scarring of the blood vessels. "In the pathogenesis of diabetic vasculopathy, such as glomerulosclerosis, downregulated PPARγ expression is associated with matrix accumulation and glomerulonephritis." (PMID 37237955, 2023). "Numerous studies have elucidated the efficacy of PPARγ agonists in ameliorating the progression of glomerulosclerosis and have indicated the direct involvement of PPARγ ligands in renoprotection." (PMID 37237955, 2023). "The PPARγ agonist troglitazone ameliorated both glomerulosclerosis and aortic medial thickening in spontaneously hypertensive rats subjected to 5/6 nephrectomy." (PMID 35308207, 2022). "PPARγ agonists inhibit glomerular sclerosis by reducing ANGPTL4 levels, while PPARα reduces ANGPTL4 levels and relieves tubulointerstitial damage." (PMID 32280690, 2020). "The PPARγ agonist rosiglitazone has been shown to inhibit mesangial cell proliferation, serine protease activity, and TGFβ expression, while activating the TGFβ-Smad3 signaling pathway, thereby preventing the progression of glomerular sclerosis." (PMID 40442892, 2025). "In contrast, overexpression of PPARγ maintained glomerulosclerosis and alleviated renal injury." (PMID 36339588, 2022). "Similarly, we and others have found that a combination of aldosterone synthase inhibitor and ARB, or a combination of proliferator-activated receptor γ (PPARγ) agonist and ARB, induced more regression of glomerulosclerosis than monotherapy in the 5/6 nephrectomy model." (PMID 35682697, 2022).
Impaired glucose tolerance (13 papers, 2009 to 2025). An abnormal resistance to glucose, i.e., a reduction in the ability to maintain glucose levels in the blood stream within normal limits following oral or intravenous administration of glucose. "The TT genotype of rs3856806 in PPARγ was associated with increased risk of impaired glucose tolerance (T allele: OR: 1.46, 95%CI: 1.055–2.017, P = 0.022; TT: OR: 1.58, 95%CI: 1.104–2.761, P = 0.032)." (PMID 29849618, 2018). "The GG genotype of rs2920502 in PPARγ was associated with decreased risk of impaired glucose tolerance (G allele: OR: 0.818, 95%CI: 0.526–0.969, P = 0.042; GG: OR: 0.715, 95%CI: 0.527–0.97, P = 0.031)." (PMID 29849618, 2018). "Activators of both PPARα and PPARγ have been shown to improve insulin sensitivity and normalize impaired glucose tolerance in both humans and rodent models of IR." (PMID 32290353, 2020). "In a number of different contexts the reductions in the expression of either PGC-1α or PPARγ in the adipose tissue have been shown to result in impaired glucose tolerance." (PMID 29678181, 2018). "In the same study treatment with the PPARγ agonist pioglitazone increased the SCD expression and insulin sensitivity in subjects with impaired glucose tolerance." (PMID 19689798, 2009).
intrauterine growth restriction (13 papers, 2013 to 2025). "Compromised placental PPARγ leads to fetal adipogenesis deficiency and intrauterine growth restriction, reversible by placenta‐targeted PPARγ activation." (PMID 39951006, 2025). "Furthermore, dysregulation of both PPARα and PPARγ in the placenta has been implicated in common complications of pregnancy, such as gestational diabetes mellitus, intrauterine growth restriction, and preeclampsia." (PMID 36359869, 2022). "In rodents, maternal DHA supplementation has been shown to restore intrauterine growth restriction-induced decreased levels of histone H4K20 methylation at the PPARγ promoter gene in the lung to normal values." (PMID 34578953, 2021). "Fetal growth restriction also had separate effects on immune development (lower lymphocyte and helper T cell counts) as well as lower expression of PPARG and TGFB1." (PMID 34684311, 2021). "PPARγ signaling pathway may be the therapeutic target for intrauterine growth restriction." (PMID 26227476, 2015). "Low birth weight (LBW), often due to intrauterine growth restriction, may induce epigenetic changes (e.g., IGF2 and PPARG methylation), impairing glucose metabolism and increasing risks of MUHPs (MUHO/MUNW)." (PMID 40662170, 2025). "PPARγ pathway is also important in the intrauterine growth restriction (IUGR) that occurs when a fetus fails to reach optimal growth potential in utero, frequently as a result of maternal hypertensive disorders and uteroplacental insufficiency." (PMID 27688818, 2016). "However, the role of PPARγ in adaptation of the uteroplacental vasculature that may lead to placental hypoperfusion and fetal growth restriction during pregnancy is not known." (PMID 23888144, 2013).
triple-negative breast carcinoma (13 papers, 2013 to 2025). An invasive breast carcinoma which is negative for expression of estrogen receptor (ER), progesterone receptor (PR), and human epidermal growth factor receptor 2 (HER2). "A metastasis ex vivo culture from a patient diagnosed with triple-negative breast cancer demonstrated a synergistic upregulation of PPARγ with the combination of Pioglitazone and Cobimetinib." (PMID 39273076, 2024). "To test the possibility of inducing adipogenesis in heavily pretreated, metastatic triple-negative breast cancer patients, we compared PPARγ expression using IHC staining, following 5 days of ex vivo treatment." (PMID 39273076, 2024). "CDK5 mediates stemness in triple-negative breast cancer (TNBC) by phosphorylating Peroxisome proliferator-activated receptor gamma (PPARγ) at S273, which curbs its E3 ligase activity and releases epithelial splicing regulatory protein 1 (ESRP1)." (PMID 37993880, 2023). "Moreover, a novel small molecule AMPK activator, OSU-53 derived from inactive peroxisome proliferator-activated receptor gamma (PPARγ), was reported to inhibit the proliferation of the triple-negative breast cancer, a disease for which there are limited therapeutic options." (PMID 23875169, 2013). "Analysis of gene expression using bc-GenExMiner showed that the mRNA levels of FABP, ADIPOQ, PPARG, CD36, PPARGC1A, and CREBBP were significantly lower in basal-like and triple-negative breast cancer (TNBC) cells than in non-basal-like and non-TNBC cells." (PMID 36114448, 2022).
type 1 diabetes (13 papers, 2005 to 2025). "Next, we discovered eight gene polymorphisms (ORMDL3, SPHK2, B4GALNT1, SLC1A5, GALC, PPARD, PPARG and B4GALT1) involved in sphingolipid metabolism that contribute to the genetic predisposition to type 1 diabetes." (PMID 29671030, 2018). "Recent studies showed that PPARγ was decreased in elderly AF patients and hypertensive AF patients, while PPARγ agonists could inhibit atrial remodeling in AF models and prevent new onset AF in patients with non-insulin dependent diabetes." (PMID 27342818, 2016). "For most of the genes analyzed, transcripts levels were markedly decreased in response to type 1 diabetes except PPARγ and TNFα in eWAT, MCP1 in scWAT and PPARγ, IL6 and TNFα in rWAT." (PMID 25170835, 2014). "IMD treatment reversed advanced glycation end products-mediated M1 macrophage polarization and impaired bone regeneration in type 1 diabetes mellitus (T1DM), which was partially achieved by the peroxisome proliferator-activated receptor γ (PPARγ)-mediated inhibition of NF-κB signaling." (PMID 37745233, 2023).